FTL (ferritin light chain)
Diseases named in the same sentence as FTL in open-access papers (continued):
Sharing a sentence is not in itself a finding about the gene and the disease.
dementia (1 paper, 2024). Loss of intellectual abilities interfering with an individual's social and occupational functions. "In contrast, microglia bearing markers of dystrophic morphology (FTL+) did not accumulate with pathology or dementia status." (PMID 38397909, 2024).
diabetes (1 paper, 2025). "The increased expression of TFR1, FTH, and FTL indicates that liver injury in diabetes patients may be caused by iron death." (PMID 40072057, 2025).
dilatation (1 paper, 2022). "Whereas LV ferritin (FTL and FTH) correlated positively with LV dilatation, ferritin-bound Fe3+ was negatively related to the same echocardiographic parameters." (PMID 35162949, 2022).
Esophageal carcinoma (1 paper, 2025). A primary or metastatic malignant neoplasm involving the esophagus. "FTL has higher expression in many cancers than in adjacent normal tissues especially in Esophageal carcinoma (ESCA)." (PMID 41281761, 2025).
gastric cancer (1 paper, 2022). A primary or metastatic malignant neoplasm involving the stomach. "For example, FTL protein is significantly higher in gastric cancer than in paracancerous tissues." (PMID 36536381, 2022).
head and neck cancer (1 paper, 2020). A primary or metastatic malignant neoplasm affecting the head and neck. "Both FTL and FTH1 stained strongly in head and neck cancer tissues compared to normal and higher expression was observed with metastasis, however further analyses of public data found FTL had no prognostic significance but high FTH1 mRNA predicted poor survival." (PMID 32328462, 2020).
head and neck squamous cell carcinoma (1 paper, 2021). A squamous cell carcinoma that arises from any of the following anatomic sites: lip and oral cavity, nasal cavity, paranasal sinuses, pharynx, larynx, and salivary glands. "We previously showed that FTH1 and FTL have positive linear correlation and the protein expression levels of both were higher in head and neck squamous cell carcinoma (HNSC) tumor tissues compared with normal tissues, and that elevated FTH1 was related to poorer prognosis." (PMID 33864445, 2021). "We previously showed that expression of ferritin light chain (FTL) and ferritin heavy chain (FTH1) subunits is increased in head and neck squamous cell carcinoma (HNSC)." (PMID 33864445, 2021).
Hepatomegaly (1 paper, 2022). Abnormally increased size of the liver. "What is more, both FTL and ferritin-bound Fe3+ were strongly inversely related to hepatomegaly." (PMID 35162949, 2022). "Therefore, it seems that HF-induced hepatic passive congestion producing liver enlargement is related to a decreased iron storage ability and enhanced erythropoiesis since hepatic FTL, ferritin-bound Fe3+ and hematological parameters were correlated with hepatomegaly." (PMID 35162949, 2022).
influenza infection (1 paper, 2025). "It has been shown that influenza infection reduces the expression of genes for iron uptake proteins and decreases the expression of genes for iron storage proteins such as ferritin light (FTL) and heavy (FTH) chains." (PMID 41346583, 2025). "Less is known about the influence of influenza infections on iron metabolism, where this study identified FTH1 and FTL as top DEPs, but it could be reflective of macrophage and/or IL-6 responses." (PMID 41346583, 2025).
iron (1 paper, 2025). "Nevertheless, analysis of transcriptional levels of FTH1 and FTL genes from public databases can also give clues for the correlation between macrophage activation and prognosis in iron overloaded AML patients." (PMID 40881683, 2025).
L-ferritin deficiency (1 paper, 2019). "L-ferritin deficiency is characterized by haploinsufficiency of the FTL protein in autosomal dominant L-ferritin deficiency, or complete loss of function in autosomal recessive L-ferritin deficiency." (PMID 30678075, 2019). "The inactivation of one allele of FTL, which occurs in the two described heterozygous cases of autosomal dominant L-ferritin deficiency, produces a significant reduction of L-ferritin in serum." (PMID 30678075, 2019). "In this study, we have identified two new cases of autosomal dominant L-ferritin deficiency, one due to a new mutation in intron 3 of the FTL gene that most probably affects splicing." (PMID 30678075, 2019). "Here, we identified two novel FTL variants that cause dominant L-ferritin deficiency and HHCS (c.375+2T > A and 36_42delCAACAGT, respectively), and one previously reported variant (Met1Val) that causes dominant L-ferritin deficiency." (PMID 30678075, 2019).
liver disorder (1 paper, 2018). A disease involving the liver. "FTL is used as a reliable blood marker of liver disorders in human medicine, and it would be interesting to further explore the FTL expression levels in blood as a surrogate and less invasive measurement of liver condition and oxidative stress in fish." (PMID 29433420, 2018).
lung fibrosis (1 paper, 2026). "Our findings identify YY1/FTL-mediated ferroptosis as a key mechanism by which PS-NPs induce pulmonary fibrosis." (PMID 41560817, 2026). "Taken together, these findings suggest that in PS-NPs-induced pulmonary fibrosis, potent positive transcription factors such as HIF-1α and NRF2 are strongly activated and exert a sustained upward drive on FTL expression." (PMID 41560817, 2026). "In the current study, we demonstrate that PS-NPs trigger an early, compensatory upregulation of FTL in lung epithelial cells, which is transcriptionally regulated by YY1 through its binding to the FTL promoter, thereby promoting ferroptosis and pulmonary fibrosis in vitro and in vivo." (PMID 41560817, 2026).
lupus (1 paper, 2022). "Furthermore, the mRNA levels of FTH and FTL, encoding the heavy chain and light chain of human ferritin, respectively, and the protein levels of ferritin were markedly increased in lupus CD4+ T cells." (PMID 35499082, 2022).
malignant mesothelioma (1 paper, 2023). A malignant neoplasm of the pleura or peritoneum, arising from mesothelial cells. "The other subunit of ferritin, the ferritin light chain (FTL), is able to affect p27, p21, cyclin-dependent kinase 2 (CDK2), and retinoblastoma protein (pRB) expression, increasing the proliferative capacity of malignant mesothelioma cells and promoting the cell cycle." (PMID 37626858, 2023).
myopia (1 paper, 2021). "Among the validation results, the abundance of TF was increased in the high myopia group, while FTL and FTH1 expression were both reduced in the high myopia group compared to the low myopia group." (PMID 34660571, 2021). "Furthermore, TMT analysis and PRM validation revealed that the expression of ferritin light chain (FTL, P02792) and ferritin heavy chain (FTH1, P02794) was negatively associated with myopia development, while the expression of serotransferrin (TF, P02787) was positively related to myopia status." (PMID 34660571, 2021).
neuroblastoma (1 paper, 2023). Neuroblastoma (NB) is the most common solid, extracranial childhood tumor. "A recent proteomic study revealed that upregulation of ATG7 was accompanied by the upregulation of ferritinophagy-related proteins, such as LC3, ferritin (FTL, FTH1), and NCOA4 in an arsenic trioxide-treated neuroblastoma cell line." (PMID 37522124, 2023).
pantothenate kinase-associated neurodegeneration (1 paper, 2013). "In addition to the core syndromes of pantothenate kinase-associated neurodegeneration (PKAN, NBIA1) and PLA2G6-associated neurodegeneration (PLAN, NBIA2), several other genetic causes have been identified (including FA2H, C19orf12, ATP13A2, CP and FTL)." (PMID 23814539, 2013).
prostate carcinoma (1 paper, 2026). A carcinoma that arises from epithelial cells of the prostate gland.
restless legs syndrome (1 paper, 2022). A condition that occurs while resting or lying in bed; it is characterized by an irresistible urgency to move the legs to obtain relief from a strange and uncomfortable sensation in the legs. "It has been reported that patients who lack ferritin light chain (FTL), an abnormality in iron metabolism, experienced atypical restless legs syndrome." (PMID 36299273, 2022).
schizophrenia (1 paper, 2013). A major psychotic disorder characterized by abnormalities in the perception or expression of reality. "Also, we observed three SZUP genes (BAZ1A, TMEM176A, and FTL) in this module in the control network, but not in the schizophrenia network." (PMID 24070017, 2013).
steatosis (1 paper, 2021). Increased lipid within the cytoplasm of cells. "For the “ferroptosis” pathway three genes were higher (FTL, ATG5, and MAP1C3A) and two were lower in steatosis (SLC40A1 and MAP1LC3C)." (PMID 34869521, 2021).
tauopathies (1 paper, 2025). "The higher level of FTL association with phospho-tau lesions detected by proteomics in CBD compared to AD and to a lesser extent other tauopathies, is likely driven by the high abundance of FTL + APs in CBD." (PMID 40082954, 2025).
tendinopathy (1 paper, 2022). "Furthermore, we found that the expression of FTH and FTL increased in tendinopathy, while the expression of TfR1 decreased; a trend that was reversed after FA treatment." (PMID 35582962, 2022).
thyroid diseases (1 paper, 2025). "However, similar to FTL, further studies are required to confirm these results and their association with other thyroid diseases." (PMID 39807704, 2025).
tuberculosis (1 paper, 2023). A chronic, recurrent infection caused by the bacterium Mycobacterium tuberculosis. "In addition, a high abundance of FTH1 and FTL is found in the cellular rim of tuberculosis (TB) cavitary granulomas." (PMID 37066876, 2023).
tuberculous meningitis (1 paper, 2012). "We validated amphiphysin, neurofascin and ferritin light chain using immunohistochemistry which confirmed their differential expression in tuberculous meningitis." (PMID 23198679, 2012).
viral infection (1 paper, 2024). "Notably, the protein levels of FTL in the SUIT-2/shFTH1#3 cells were significantly altered after shFTH1 viral infection compared with those in either the SUIT-2 or the Scr cells; therefore, we specifically selected the sh#1 and sh#4 FTH1-knockdown clones for further analyses." (PMID 39294443, 2024).
tumor (60 papers, 2014 to 2025). "Tissue microarray analysis showed that lower FTL expression was associated with shorter tumor metastasis and survival, and the higher the FTL level, the better the treatment effect." (PMID 36897430, 2023). "FTH1 also serves as a novel marker for macrophages, and FTL is a prognostic marker in tumor-associated macrophages, along with CD163." (PMID 28957348, 2017). "In addition, FTL was highly expressed in HCC tumor tissue and served as a promising prognostic and diagnostic factor in HCC patients." (PMID 35651950, 2022). "miR-133b-3p targets MET (involved in invasive tumour growth), the gene encoding ferritin light chain (FTL), lncRNA LINC00467 (promoting CRC cell resistance against 5FU), a component of the nuclear pore complex proto-oncogene nucleoporin 214 (NUP214) and some others." (PMID 32610706, 2020). "Secondly, the M2-polarized macrophages are mainly composed of M2-like tumor-associated macrophages (TAMs) with tumor-promoting characteristics (CD163, FTH1, FTL, TIMP1), and there is a polarization from M1 to M2." (PMID 40948800, 2025). "Immunohistochemistry (IHC) results displayed that FTL-expressing cells were detected more in most ESCC tissues (about 65% staining) but detected rarely (less than 5% staining) in non-tumor tissues." (PMID 41281761, 2025). "While, NCOA4 exerted its function of inhibiting tumor development by affecting FTL to regulate the ESCC sensitivity to ferroptosis." (PMID 41281761, 2025). "Functional studies have shown that FTL promoted tumor growth, tolerated oxidative stress, reduced the sensitivity of ESCC cells to ferroptosis, facilitated epithelial-mesenchymal transition (EMT) and recruited more macrophages to promote metastasis." (PMID 41281761, 2025). "The expression levels of ferritin subunits FTL and FTH1 were positively correlated with tumor infiltration by tumor-associated macrophages and T regulatory cells in most solid tumors, suggesting an important role in regulating tumor immunity." (PMID 37575948, 2023). "FPN, TfR1, FTH, and FTL showed higher expression in tumor tissues, indicating increased iron usage by cancer." (PMID 37623041, 2023). "At the same time, immunohistochemistry showed that the expression of FTH1, FTL in tumor tissues was significantly higher than that in para-tumor tissues." (PMID 37555866, 2023). "FTL levels in cancer tissue, tumor cells, and serum were negatively correlated with patient survival." (PMID 36910614, 2023). "Among the proteins whose expression levels were decreased upon SMAC depletion was ferritin light chain (FTL), a subunit of ferritin that is the main form of iron storage protein and is known to influence tumor immunity, which decreased over 5-fold." (PMID 36185255, 2022). "It has been reported that immunomodulatory proteins and chemokines, including CSF-1, CCL2, FTH, FTL, and TGFβ, are highly enriched in exosomes produced by hypoxic tumor cells." (PMID 36224346, 2022). "To verify the expression level of FTL in normal tissue and tumor tissue in HCC patients, we obtained three different HCC cohorts, including the TCGA-LIHC cohort, ICGC HCC cohort, and GSE14520 cohort." (PMID 35651950, 2022). "IRF8 was associated with depleted CD8+ T cells in the GC.The transcription factor RBPJ was overexpressed in the tumor-infiltrating Tregs.DC cells expressed more inhibitory receptors in GC tissues, for example, FTL and IL8." (PMID 35785171, 2022). "The expression profile of TRFC, FTH1, and FTL is positively correlated with tumor pathological grade and affects tumor progression like renal cell carcinoma, head and neck squamous cell carcinoma, and breast cancer." (PMID 35126346, 2021). "In many cancers, FTL and FTH1 levels was significantly positively correlated with tumor infiltration by tumor-associated macrophages and T regulatory cells." (PMID 33864445, 2021).
tumor (continued). "We constructed two patient-derived xenograft (PDX) models with 4-HNE low (PDX #1) and 4-HNE high (PDX #2) and found that PKE inhibited tumor growth and FTL levels in the PDX #1 model to a greater extent than it did in the PDX #2 models." (PMID 34765600, 2021). "To clarify the potential role of FTL and FTH1 in tumor immunity, we next examined correlations between the expressions of FTL and FTH1 and 47 distinct immune-related markers using Pearson Correlation Coefficient analysis." (PMID 33864445, 2021). "In good correspondence with this, resected tumour tissue from both patients immunoreacted with anti-ferritin antibodies, especially for the FTL subunit, GBM specimens showing significantly (p < 0.005) higher labelling indices." (PMID 32203223, 2020). "Cancer cells of various tumor entities develop an iron retaining phenotype by upregulating FTL, FTH, TfR1, and IRP1/2, while downregulating the iron exporter FPN." (PMID 32106629, 2020). "While in recent years, a growing number of studies have revealed the close relationship between FTL and tumor malignancies." (PMID 32677981, 2020). "The expression in cancer cells of genes, such as the transferrin receptor (TfR1), ferritin light chain (FTL), and the iron regulatory protein (IRP)-2, is associated with poor prognosis, a higher grade of tumor, and increased resistance to chemotherapy." (PMID 32426284, 2020). "The anti-tumor activity of these two versions of EcrFTL, the Fh8FTL and Fh8-cleaved FTL, is under evaluation." (PMID 25152749, 2014). "Nevertheless, PprFTL presented an anti-tumor activity identical to FTL and enhanced tumor biomarker capacity." (PMID 25152749, 2014). "The results showed that FTL has a strong carcinogenic ability, could promote cell growth in vitro, promote tumor formation in vivo, and significantly reduce the sensitivity of ESCC cells to ferroptosis." (PMID 41281761, 2025). "Furthermore, the tumor growth mice model also showed that FTL overexpression significantly increased the tumor growth in vivo." (PMID 41281761, 2025). "Significantly up-regulatedproteins in tumor tissue included ferritin light chain (FTL, adj." (PMID 40574313, 2025). "While showing signs of tumor adaptation, the margin retained normal tissue characteristics, with downregulation of genes involved in iron accumulation, detoxification, and immune response (FTL, SERPINA3, IGHA1)." (PMID 40431665, 2025). "Also, the tumor growth mice model showed that NRF2 knockdown impaired FTL increasing tumor growth in vivo." (PMID 41281761, 2025). "Furthermore, our single-cell transcription atlas of primary and metastatic ecosystems in ESCC had also showed that FTL had higher expression in metastasis than primary tumor." (PMID 41281761, 2025). "Also, the tumor growth mice model showed that knockdown of NRF2 and Brusatol significantly reversed FTL increasing tumor growth in vivo." (PMID 41281761, 2025). "Furthermore, the tumor growth mice model also showed that FTL knockdown decreased the tumor growth in vivo." (PMID 41281761, 2025). "Therefore, serum FTL level appears to be a useful biomarker for selecting treatment regimens and monitoring tumor progression." (PMID 36910614, 2023). "Our study demonstrated that inhibiting FTL in TAMs attenuates tumor angiogenesis." (PMID 37441589, 2023). "Interestingly, only the ferroptosis pathway was the most relevant Biological Process to the tumor and three genes were mapped to the ferroptosis pathway, which included transferrin (TF), ceruloplasmin (CP), and ferritin light chain (FTL)." (PMID 35340268, 2022). "Finally, TIMINER was employed to further analyze the associations between FTL and FTH1 expressions and other subtypes of tumor-infiltrating immune cells." (PMID 33864445, 2021).